PIGR (polymeric immunoglobulin receptor)
Diseases named in the same sentence as PIGR in open-access papers (continued):
Sharing a sentence is not in itself a finding about the gene and the disease.
COVID-19 (5 papers, 2021 to 2025). A disease caused by infection with severe acute respiratory syndrome coronavirus 2. "Recent findings have shown a marked reduction in the expression of the polymeric Ig receptor (pIgR) in COVID-19 patients." (PMID 39066171, 2024). "The loss of this biological function may render the airways more susceptible to SARS-CoV-2 infection, which is corroborated by the low pIgR levels in COVID-19 patients with severe disease." (PMID 39066171, 2024). "We do not know whether other cellular receptor such as the polymeric immunoglobulin receptor (pIgR) plays a role in B8-dIgA-mediated SARS-CoV-2 nasal infection." (PMID 37542391, 2023). "Cluster M3 was highly correlated to cluster M4 as indicated by a high Pearson correlation coefficient (r = 0.92) between the 2 clusters, and contains proteins with a similar alteration in COVID-19 cohorts (eg, VWF, leucine-rich α2-glycoprotein 1, galectin-1, and polymeric immunoglobulin receptor)." (PMID 40224277, 2025).
gastric cancer (5 papers, 2014 to 2025). A primary or metastatic malignant neoplasm involving the stomach. "The significant association of PIGR with T-stage was retained in esophageal cancer (p = 0.006), while in gastric cancer, PIGR expression was significantly associated with a more advanced N-stage (p = 0.043)." (PMID 24694107, 2014). "In this context, the observation of a significant association between PIGR expression and a more advanced N-stage in gastric cancer is noteworthy, since the prognostic value of PIGR was not evident in this category." (PMID 24694107, 2014).
meningitis (5 papers, 2014 to 2022). A disorder characterized by acute inflammation of the meninges of the brain and/or spinal cord. "The predominant cause of meningitis in older infants and children is Streptococcus pneumoniae, which interacts with the endothelial receptors polymeric immunoglobulin receptor (pIgR) and platelet endothelial cell adhesion molecule-1 (PECAM-1 or CD31) to invade the CNS." (PMID 35250814, 2022). "Binding of RrgA to BBB endothelial receptors (PECAM-1 and pIgR) promotes bacterial entry and meningitis development." (PMID 33633703, 2021). "The aim of this study was to investigate the roles of PAFR and pIgR in S. pneumoniae adhesion to brain endothelial cells in a bacteremia-derived meningitis model." (PMID 24841255, 2014). "This indicates that interaction of PspC to pIgR might be important for the development of meningitis." (PMID 24841255, 2014). "The aim of this research was to clarify whether pneumococci adhering to the brain endothelium co-localize with either PAFR or pIgR during the events preceding meningitis." (PMID 24841255, 2014). "In addition, we also demonstrated that pIgR present in human endothelial cell lysates binds to the bacteria, implicating that pIgR may also be involved in bacterial transcytosis of endothelial cells and thus contribute to the development of meningitis." (PMID 24841255, 2014).
bladder cancer (4 papers, 2012 to 2014). "Similar associations have previously been described in studies on PIGR expression in oesophageal, colorectal, non-small cell lung, endometrial and bladder cancer." (PMID 24568264, 2014). "A study concerning bladder cancer lays forward a hypothesis that PIGR expression is associated with good prognosis, however, the study also points out the need for further research." (PMID 24568264, 2014).
emphysema (4 papers, 2016 to 2024). "This implies that the invasion of SIgA-deficient trachea by bacteria is a major contributor to inflammation and emphysema in pIgR-deficient (pIgR-/-) mice." (PMID 38228603, 2024). "In SIgA-deficient (pIgR−/−) mice, we show that endogenous bacteria stimulate adaptive immune activation in the airways and that T lymphocytes directly contribute to emphysema and small airway wall thickening." (PMID 32968197, 2021). "12-month-old pIgR-deficient mice (which were maintained in standard housing for 6 months) demonstrated similar levels of airway wall remodelling, emphysema and inflammation to 6-month-old pIgR−/− mice raised in standard housing." (PMID 27046438, 2016). "We found that roflumilast blocks inflammatory cell recruitment and prevents small airway wall remodelling and emphysema that develop in response to pIgR/SIgA deficiency." (PMID 27046438, 2016). "In our models, pIgR deficiency and long-term CS exposure showed a similar degree of inflammation and COPD-like remodelling in the lungs; however, the combination of pIgR deficiency and cigarette smoking appeared to have an additive effect on small airway wall remodelling and emphysema." (PMID 27046438, 2016). "In addition, pIgR–/– mice are more susceptible to develop airway fibrosis and emphysema upon aging, indicating that altered pIgR expression could play a driving role in this disease." (PMID 34248677, 2021). "Similarly, pIgR−/− mice treated with CD8-depleting antibodies had reduced emphysema and a trend toward reduced small airway wall thickness." (PMID 32968197, 2021). "WT mice treated with CS developed a similar degree of small airway wall remodelling and emphysema compared with sham-treated pIgR−/− mice; however, CS exposure worsened COPD-like remodelling in pIgR−/− mice." (PMID 27046438, 2016).
inflammatory bowel disease (4 papers, 2014 to 2023). A spectrum of small and large bowel inflammatory diseases of unknown etiology. "However, inflammation, especially in inflammatory bowel disease, reportedly causes pIgR dysfunction." (PMID 36551783, 2022). "Patients with inflammatory bowel disease were found to have an elevated serum level of secretory IgA owing to pIgR dysfunction." (PMID 36551783, 2022). "For instance, pIgR has been demonstrated to be downregulated in the intestinal mucosa in patients with inflammatory bowel disease, and levels of pIgR expression were found to correlate with the severity of the disease." (PMID 25397670, 2014).
liver cancer (4 papers, 2021 to 2025). An epithelial or non-epithelial malignant neoplasm that arises from the liver. "Compared to traditional markers such as alpha-fetoprotein (AFP), LG3BP and PIGR show higher sensitivity and specificity in early diagnosis of liver cancer." (PMID 40433362, 2025). "For example, the identified polymeric immunoglobulin receptor is upregulated in the liver of patients with liver fibrosis and liver cancer." (PMID 36012106, 2022). "We previously found that PIGR involved in the activation of ribosome pathway and accounted for liver cancer recurrence." (PMID 33937393, 2021). "As a vital inflammatory mediator, PIGR played an important role in hepatitis B (HBV) infection, chronic liver inflammation, tumor growth, recurrence, and metastatic progression in liver cancer and pancreatic ductal adenocarcinoma." (PMID 33937393, 2021).
osteosarcoma (4 papers, 2014 to 2024). A usually aggressive malignant bone-forming mesenchymal neoplasm, predominantly affecting adolescents and young adults. "Table III demonstrates the association between pIgR expression and clinicopathological characteristics of the 136 osteosarcoma tissue samples, including age, gender, tumor location, histological type and grade." (PMID 24699841, 2014). "Positive pIgR expression was found to be associated with poor prognosis in patients with osteosarcoma (log-rank test, P<0.001)." (PMID 24699841, 2014). "In conclusion, to the best of our knowledge, this is the first study to show that positive expression of pIgR is significantly associated with a poor prognosis in osteosarcoma patients." (PMID 24699841, 2014). "Furthermore, positive pIgR expression was significantly associated with poor prognosis in patients with osteosarcoma." (PMID 24699841, 2014). "pIgR expression was assessed using quantitative polymerase chain reaction analysis in cryopreserved osteosarcoma tissues from 22 patients, as well as using immunohistochemistry in paraffin-embedded osteosarcoma tissues from 136 patients." (PMID 24699841, 2014). "Multivariate analysis revealed that positive pIgR expression in osteosarcoma tissues was an independent prognostic factor for OS following surgical resection (P<0.001)." (PMID 24699841, 2014). "In the present study, pIgR expression was analyzed in cryopreserved osteosarcoma tissues from 22 patients using qPCR analysis and was found to be expressed in 15 (68.2%) patients." (PMID 24699841, 2014). "Univariate analysis indicated that patients with positive pIgR osteosarcoma tissue expression had a significantly worse overall survival (OS) compared with patients with negative pIgR osteosarcoma expression." (PMID 24699841, 2014). "Furthermore, multivariate analysis showed that positive pIgR expression in osteosarcoma tissues was an independent prognostic factor for OS following surgical resection (P<0.001)." (PMID 24699841, 2014). "pIgR expression was subsequently assessed in paraffin-embedded osteosarcoma tissue samples from 136 osteosarcoma patients with clinical follow-up records; positive pIgR expression was identified in 93 (68.4%) of the paraffin-embedded osteosarcoma tissue samples." (PMID 24699841, 2014). "In addition, the potential of pIgR as a novel prognostic marker in patients with osteosarcoma following surgical resection was investigated." (PMID 24699841, 2014). "Among the 136 osteosarcoma samples, pIgR was observed to be expressed in 93/136 (68.4%) samples." (PMID 24699841, 2014). "qPCR analysis was performed to assess pIgR gene expression in 22 fresh frozen osteosarcoma samples." (PMID 24699841, 2014). "pIgR expression was found to be positive in 15/22 (68.2%) patients with osteosarcoma." (PMID 24699841, 2014). "Therefore, pIgR may be a novel predictor for poor prognosis in osteosarcoma patients following surgical resection and may be a promising candidate for targeted osteosarcoma therapy." (PMID 24699841, 2014). "However, the clinical significance of pIgR in osteosarcoma has yet to be elucidated." (PMID 24699841, 2014). "Univariate analysis revealed that OS for patients with a positive pIgR expression in osteosarcoma tissues was significantly poorer compared with patients with negative pIgR expression." (PMID 24699841, 2014). "The prognostic significance of negative or positive pIgR expression in osteosarcoma was assessed using Kaplan-Meier survival analysis and log-rank tests." (PMID 24699841, 2014).
pneumococcal meningitis (4 papers, 2017 to 2025). An acute purulent infection of the meninges and subarachnoid space caused by Streptococcus pneumoniae, most prevalent in children and adults over the age of 60. "Adjunct treatment with pIgR and PECAM-1 antibodies to antibiotics may prevent pneumococcal meningitis development and associated brain damage." (PMID 40709930, 2025). "Our data suggest that inhibition of pIgR and PECAM-1 has the potential to prevent pneumococcal meningitis." (PMID 28515075, 2017).
bacterial meningitis (3 papers, 2013 to 2024). Inflammation of the membranes surrounding the brain and spinal cord due to a bacterial infection. "PIGR is expressed in the endothelial cells of the blood–brain barrier and binds to the bacteria Streptococcus pneumonia (Pneumococci)—a leading causes of bacterial meningitis." (PMID 38528588, 2024). "In this regard, a recent study showed that inhibiting the brain endothelial receptors, polymeric immunoglobulin receptor and platelet endothelial cell adhesion molecule 1, reduces pneumococcal brain invasion in a bacterial meningitis model." (PMID 31251447, 2019).
coronary atherosclerosis (3 papers, 2017 to 2021). Atherosclerosis of the coronary vasculature. "A first hint in this direction was shown in a study where pIgR is associated with coronary atherosclerosis in coronary vessels of individuals chronically exposed to increased ambient concentrations of traffic air pollution." (PMID 32427855, 2020). "Candidate gene interaction studies have added much to our knowledge of air pollution and coronary atherosclerosis; our findings add to these studies by implicating additional inflammatory response genes (FCAMR and PIGR)." (PMID 28355232, 2017). "Given the proximity of the two genes, their similar functions, and LD structure we cannot completely disregard that potentially both PIGR and FCAMR are involved in mediating the effects of traffic-related air pollution on coronary atherosclerosis." (PMID 28355232, 2017).
esophageal cancer (3 papers, 2014 to 2022). A primary or metastatic malignant neoplasm involving the esophagus. "Subgroup analysis according to anatomical tumour location revealed that the prognostic impact of PIGR expression was most evident in esophageal cancer for OS and esophageal/GE junction cancer for RFS." (PMID 24694107, 2014).
liver fibrosis (3 papers, 2021 to 2022). "By identifying the associations between PIGR and liver fibrosis progression, we hope to offer novel insights into the mechanisms of liver fibrosis, even in hepatocarcinogenesis." (PMID 33937393, 2021). "Considering the underlying correlations between hepatitis virus infection, liver fibrosis, and hepatocarcinogenesis, we assumed that PIGR might participated in the liver fibrosis progression, which resulted in liver malignancies." (PMID 33937393, 2021). "Considered the pivotal roles of HSCs in the development of liver fibrosis, PIGR mRNA expression levels were identified in HSCs in GEO series including GSE11954, GSE49995, and GSE68001." (PMID 33937393, 2021). "PIGR mRNA expression in normal liver, liver fibrosis, hepatic stellate cells (HSCs), and hepatitis virus infection samples was calculated in Gene Expression Omnibus (GEO) and Oncomine databases." (PMID 33937393, 2021). "In this study, we aimed to investigate the expression of PIGR according to liver fibrosis, status of hepatic stellate cells (HSCs), and hepatitis virus infection." (PMID 33937393, 2021). "Logistic model and ROC curve were performed to evaluate the correlations between pIgR and liver fibrosis." (PMID 33937393, 2021). "The CKG automatically reproduced our previous results showing dysregulation of proteins involved in immune system regulation and inflammation, such as C7, JCHAIN, PIGR and A2M, a known marker of liver fibrosis for which CKG reported 14 publications, confirming this connection." (PMID 35102292, 2022). "In this analysis, we found that PIGR was apparently upregulated in advanced liver fibrosis." (PMID 33937393, 2021). "PIGR was correlated with liver fibrosis and might involve in hepatitis virus infection and HSC transdifferentiation." (PMID 33937393, 2021). "Given the recently established connections between PIGR, proinflammatory cytokines, and signaling pathways including JAK-STAT, NF-κB, and MAPK, our findings partly raise the underlying possibility that PIGR may facilitate liver fibrosis via proinflammatory cytokine-induced pathways." (PMID 33937393, 2021). "This study is aimed at investigating the enriched functions of polymeric immunoglobulin receptor (PIGR) and its correlations with liver fibrosis stage." (PMID 33937393, 2021).
nasopharyngeal carcinoma (3 papers, 2023 to 2025). A carcinoma arising from the nasopharyngeal epithelium. "And the expression level of PIGR was demonstrated decreased in nasopharyngeal carcinoma cells by Qi and colleagues, related to poor prognosis." (PMID 37875600, 2023). "Evidence also suggests that decreased PIGR expression correlates with tumor progression and poor prognosis in several cancers, including nasopharyngeal carcinoma, esophageal squamous cell carcinoma, gastric adenocarcinoma, lung cancer, and epithelial ovarian cancer." (PMID 40386563, 2025).
non-small cell lung carcinoma (3 papers, 2014). A group of at least three distinct histological types of lung cancer, including non-small cell squamous cell carcinoma, adenocarcinoma, and large cell carcinoma. "Furthermore, tumour progression in non-small cell lung cancer is reportedly associated with loss of PIGR expression." (PMID 24568264, 2014).
pneumococcal infection (3 papers, 2017 to 2025). Infections with bacteria of the species streptococcus pneumoniae. "Similar to the effect of pIgR deficiency, intravenous administration of the pIgR-neutralizing antibody also inhibited pneumococcal infection in the brain." (PMID 40642082, 2025). "Thus, it is possible that the observed inhibition of pneumococcal infection was a result from a depletion or inhibition of plasma pIgR." (PMID 40642082, 2025). "Further studies are needed to explore whether prophylactic pIgR enhancement serves as a therapeutic strategy for CRD patients with recurrent pneumococcal infections." (PMID 28694492, 2017). "It was also reported that mice immunized with a mucosal vaccine that induced sIgA were protected against pneumococcal infection while the same treatment was not able to induce protection against the nasal challenge with S. pneumoniae in pIgR−/− mice." (PMID 36992195, 2023).